PABPC1L (poly(A) binding protein cytoplasmic 1 like)
Description:
Poly(A)-binding protein involved in oocyte maturation and early embryo development. It is required for cytosolic mRNA polyadenylation and translational activation of maternally stored mRNA in oocytes (By similarity).
Synonyms: C20orf119; EPAB; dJ1069P2.3; PABPC1L1; OZEMA22
Tractability: PROTAC: ubiquitination databases record sites on it.
Gene: Protein-coding gene on chromosome 20 (44,910,060 to 44,959,035, forward strand). Ensembl gene ENSG00000101104.
Subcellular location: Cytoplasm
Subcellular location (Human Protein Atlas): Cytosol; Nuclear bodies
Gene Ontology:
Molecular function: poly(A) binding; mRNA 3'-UTR binding; poly(U) RNA binding; nucleic acid binding; RNA binding
Biological process: oocyte maturation; positive regulation of translation; positive regulation of gene expression
Cellular component: cytoplasm; extracellular exosome; cytoplasmic stress granule; cytosol; nucleus; ribonucleoprotein complex
Genetic constraint (gnomAD): Loss-of-function variants: 28 observed, 63.12 expected, observed/expected ratio (o/e) 0.44, 90% interval 0.33 to 0.61. The upper end of that interval is the gene's LOEUF score, 0.61, which puts it in group 2 of 6, group 1 being the genes least tolerant of losing a copy. Missense variants: 704 observed, 819.93 expected, observed/expected ratio (o/e) 0.86, 90% interval 0.81 to 0.91. Synonymous variants: 339 observed, 319.67 expected, observed/expected ratio (o/e) 1.06, 90% interval 0.97 to 1.16.
Homologues: Orthologues: macaque PABPC1L (98% identical), dog PABPC1L (87% identical), pig PABPC1L (86% identical), guinea pig PABPC1L (84% identical), rat Pabpc1l (77% identical), mouse Pabpc1l (76% identical), tropical clawed frog pabpc1l (74% identical), zebrafish pabpc1l (70% identical), chimpanzee PABPC1L (53% identical). Paralogues in human: PABPC1 (70% identical), PABPC4 (68% identical), PABPC3 (66% identical), PABPC4L (38% identical), PABPC5 (35% identical), PABPC1L2A (23% identical), PABPC1L2B (23% identical), RBMS1 (18% identical), RBMS3 (17% identical), RBMS2 (16% identical), SYNCRIP (15% identical), PUF60 (14% identical), and 12 more.
Diseases named in the same sentence as PABPC1L in open-access papers:
PABPC1L is named in the same sentence as 18 diseases in open-access papers, as found by Europe PMC text mining. Sharing a sentence is not in itself a finding about the gene and the disease. The quoted sentences say what the papers report.
colorectal cancer (7 papers, 2020 to 2025). A primary or metastatic malignant neoplasm that affects the colon or rectum. "This study aimed to investigate the expression of lncRNAs associated with the PABPC1L gene in the NMD pathway of colorectal cancer (CRC) through assessment of their expression in paired CRC tissues and adjacent non-tumor (ANT) tissues." (PMID 41357316, 2025). "For instance, PABPC1L is highly expressed in colorectal cancer and is significantly correlated with its clinical stage and prognosis." (PMID 33193734, 2020). "In addition, depletion of PABPC1L in colorectal cancer cells inhibits cell proliferation and migration." (PMID 34830961, 2021). "The depletion of PABPC1L can inhibit the expression level of p-AKT and p-PI3K and suppress the process of proliferation, migration, and invasion in colorectal cancer cells." (PMID 35211477, 2021). "Another study showed that PABPC1L depletion inhibited proliferation and migration by blocking the AKT pathway in human colorectal cancer cells." (PMID 33229623, 2020).
Infertility (3 papers, 2023). "Our findings reveal the important roles of PABPC1L in human oocyte maturation and add a genetic potential candidate gene to be screened for causes of infertility." (PMID 37052235, 2023). "We then performed mutational screening of PABPC1L in a cohort of 504 infertile individuals with abnormalities in fertilization and early embryonic development." (PMID 37052235, 2023). "Seven rare variants in PABPC1L were identified in five infertile females mainly characterized by oocyte maturation arrest followed a recessive inheritance pattern." (PMID 37052235, 2023). "We first identified three infertile individuals from three independent families (families 1–3) harboring bi‐allelic variants in PABPC1L (GenBank: NM_001124756.2)." (PMID 37052235, 2023). "Our findings provide direct evidence for the important role of PABPC1L in female reproduction and thus add a potential genetic candidate gene to be screened for causes of infertility patients in the clinic." (PMID 37052235, 2023). "Finally, we constructed three strains of Pabpc1l KI mice corresponding to patient‐derived variants and found that female mice were infertile." (PMID 37052235, 2023). "In this study, we identified five individuals with bi‐allelic variants in PABPC1L, which accounts for 0.26% of our cohort of 1,898 infertile woman (1,394 with oocyte maturation arrest and 504 with abnormalities in fertilization and early embryonic development)." (PMID 37052235, 2023). "In vivo, three strains of Pabpc1l knock‐in (KI) female mice were infertile." (PMID 37052235, 2023). "Second, although we have confirmed the pathogenicity of the PABPC1L variants and provided the exploration of the mechanism leading to phenotype, we have not found a possible treatment to overcome infertility." (PMID 37052235, 2023). "In the ClinVar database, a pathogenic missense variant in PABPC1L was reported in 3 sisters from a consanguineous Turkish family with OMA; however, no functional evidence was provided, underscoring a common shortcoming in the implication of human infertility variants." (PMID 37073822, 2023). "Importantly, PABPC1, PABPC1L, and PABPC3 expressions are perturbed in infertile men." (PMID 37176068, 2023).
prostate carcinoma (2 papers, 2021 to 2023). A carcinoma that arises from epithelial cells of the prostate gland. "PABPC1L is an RNA binding protein that is overexpressed in different cancer types, including prostate cancer, and its overexpression is associated with worse DFS." (PMID 34830961, 2021).
rectal cancer (2 papers, 2018 to 2021). A primary or metastatic malignant neoplasm that affects the rectum. "A microarray analysis has shown that PABPC1L was upregulated in preoperative radiotherapy patients with rectal cancer." (PMID 34830778, 2021). "The gene, PABPC1L, is known to be involved in transcription and has been shown to be down-regulated by preoperative radiotherapy in rectal cancer." (PMID 29547645, 2018).
colorectal tumors (1 paper, 2025). "Together, these findings highlight PABPC1L, SNHG17 and SNHG1 as the most promising candidate biomarkers for distinguishing colorectal tumors from adjacent non-tumor tissues, with PABPC1L showing the most favorable balance of sensitivity and specificity." (PMID 41357316, 2025).
female infertility (1 paper, 2023). Diminished or absent ability of a female to achieve conception. "In this study, we identified compound heterozygous and homozygous pathogenic variants in PABPC1L (GRCh37, GenBank: NM_001124756.2) that are responsible for female infertility mainly characterized by oocyte maturation arrest." (PMID 37052235, 2023). "Our findings suggest a causal relationship between PABPC1L and female infertility and reveal important roles for PABPC1L in human oocyte maturation." (PMID 37052235, 2023). "In conclusion, we identified bi‐allelic pathogenic variants in PABPC1L that cause oocyte maturation arrest and female infertility." (PMID 37052235, 2023). "Here, we identified compound heterozygous and homozygous variants in PABPC1L that are responsible for female infertility mainly characterized by oocyte maturation arrest in five individuals." (PMID 37052235, 2023). "This strategy might provide a possible treatment option to overcome female infertility caused by PABPC1L dysfunction, but additional experiments should be pursed for evaluating effectiveness to embryonic development." (PMID 37052235, 2023). "On the other hand, patient‐derived variants (c.290G>A (p.Gly97Asp), c.410C>T (p.Ser137Phe), and c.1501C>T (p.Arg501Trp)) disrupted the translational activation of PABPC1L and resulted in female infertility characterized by oocyte maturation arrest." (PMID 37052235, 2023). "Together, these results indicate that PABPC1L pathogenic variants lead to increased Mos expression and abnormal activation of Mos‐MAPK pathway in zygotes, ultimately resulting in early embryonic arrest and female infertility in Pabpc1l KI mice." (PMID 37052235, 2023).
renal carcinoma (1 paper, 2024). A carcinoma arising from the epithelium of the renal parenchyma or the renal pelvis. "The results of the TCGA-KIRC cohort showed that either in paired or unpaired renal cancer tissues, except for CLIC5, which was in a low expression state, the remaining four genes (MXD3, NUF2, PABPC1L, and PLK1) were in a high expression." (PMID 38546385, 2024).
renal clear cell carcinoma (1 paper, 2024). "Similarly, CLIC5 expression was found to be lower than that of normal kidney tissues in renal clear cell carcinoma tissues extracted from our research center, while MXD3, NUF2, PABPC1L, and PLK1 were significantly higher in renal clear cell carcinoma tissues than in normal kidney tissues." (PMID 38546385, 2024).
tumor (5 papers, 2020 to 2025). "Among the four transcripts, only PABPC1L emerged as an independent predictor, with higher expression significantly associated with increased odds of tumor status (β = 0.172, OR = 1.19, 95 % CI 1.00–1.44, p < 0.05)." (PMID 41357316, 2025). "Three transcripts were significantly overexpressed in tumor tissue: PABPC1L (mean fold-change ≈ 5.20, 95 % CI 2.30–11.85, P = 0.0003), SNHG17 (mean fold-change ≈ 5.46, 95 % CI 2.04–14.50, P = 0.001), and SNHG1 (mean fold-change ≈ 5.82, P = 0.0086)." (PMID 41357316, 2025). "PABPC1L is a key gene in tumor progression and postoperative prognosis, while inhibition of PABPC1L suppresses CRC cell growth and metastasis." (PMID 36925638, 2023). "Our observation of strong tumor-specific co-expression among SNHG17, SNHG1 and PABPC1L; together with the reciprocal association between SNHG17 and RUSC1-AS1 in multivariable models suggest a model in which lncRNA networks and translation regulators act in concert to drive tumor cell phenotypes." (PMID 41357316, 2025). "By contrast, tumor specimens showed a tighter, tumor-specific module: SNHG17 correlated strongly with SNHG1 (ρ = 0.61, p < 0.01) and with PABPC1L (ρ = 0.46, p < 0.05), while PABPC1L and SNHG1 were also significantly associated in tumor (ρ = 0.50, p < 0.01)." (PMID 41357316, 2025). "Our study identified a tumor-specific expression module comprising PABPC1L, SNHG17 and SNHG1, with RUSC1-AS1 incorporated into the tumor co-expression network." (PMID 41357316, 2025). "In this paired analysis of 43 CRC patients, we found consistent upregulation of PABPC1L, SNHG17 and SNHG1 in tumor tissues relative to ANT samples, while RUSC1-AS1 showed a non-significant trend toward increased expression." (PMID 41357316, 2025). "Collectively, these results indicate that SNHG17, PABPC1L and SNHG1 form a coordinated expression module in CRC samples and that RUSC1-AS1 is incorporated into this tumor-specific network." (PMID 41357316, 2025). "PLAUR, PABPC1L, SLC16A12, NFE2L3, and KCNAB1 presented significantly different expression levels between tumor tissues and normal tissues." (PMID 35211477, 2021). "The results indicated that, as NOL12, PABPC1L, RNASE2, RPL22L1, and OASL expression increased, tumor grade, AJCC stage, T stage, and M stage in KIRC patients increased." (PMID 33229623, 2020). "NOL12, PABPC1L, RNASE2, RPL22L1, OASL, and YBX3 expression were significantly positively correlated with tumor grade and AJCC stage, while RBM47 expression was negatively correlated with tumor grade and AJCC stage." (PMID 33229623, 2020). "For example, high expression of PABPC1L was observed in 81.4 % of tumor samples versus 41.9 % of normal samples, and high SNHG1 expression in 79.1 % of tumors versus 46.5 % of ANT samples." (PMID 41357316, 2025). "Multivariable modeling indicated that PABPC1L made the strongest independent contribution to discrimination of tumor versus ANT samples within the four-gene panel, whereas the lncRNAs contributed to a coordinated tumor-specific co-expression module." (PMID 41357316, 2025). "No other clinicopathologic or demographic variable, including sex, BMI group, tumor location, TNM stage, chronic disease status, or family history of cancer, showed a significant relationship with the expression of RUSC1-AS1, SNHG17, PABPC1L, or SNHG1 (all p > 0.05)." (PMID 41357316, 2025).
cancer (4 papers, 2020 to 2025). A tumor composed of atypical neoplastic, often pleomorphic cells that invade other tissues. "These genes are PLAUR, UCN, PABPC1L, SLC16A12, NFE2L3, and KCNAB1, and some of them have been previously reported in multiple types of cancer." (PMID 35211477, 2021).
PABPC1L also shares sentences with these, for which no sentence is quoted: infection (2 papers); anaphylactic shock (1); Chronic colitis (1); colitis (1); colon cancer (1); peritonitis (1); viral infections (1); ZIKV infection (1).